LEP (leptin)
Diseases named in the same sentence as LEP in open-access papers (continued):
Sharing a sentence is not in itself a finding about the gene and the disease.
Insulin resistance (continued). "Both altered cortisol secretion and sleeping/feeding pattern will cause an increase in leptin after the meal (at night) and a decrease in adiponectin (ultradian pulsatility) leading to a significantly increased insulin resistance." (PMID 32775407, 2020). "In fact, leptin replacement successfully normalized or improved most of the phenotypes in patients with congenital leptin deficiency, including decrease in insulin resistance, improvement of lipid profile, and remarkable weight loss." (PMID 32655492, 2020). "The adipocytokine signaling pathway includes the signaling cascades caused by adipocytokines (TNF-α, leptin and adiponectin), which are pivotal signaling molecules associated with insulin resistance." (PMID 32655508, 2020). "This study aimed to investigate the association between adiponectin and leptin with insulin resistance in patients with liver cirrhosis, as well as to assess the influence of disease severity on insulin resistance and metabolic status." (PMID 32092909, 2020). "We investigated the association between insulin resistance, serum adiponectin, insulin, and leptin with hepatic steatosis in a cohort of liver transplant recipients." (PMID 32728230, 2020). "Elevated blood leptin level is associated with insulin resistance and the risk of metabolic syndrome." (PMID 33551872, 2020). "Leptin is an adipokine and due to the loss of adipose tissue, lipodystrophies are generally associated with partial or total leptin deficiency that eventually causes neuroendocrine and metabolic abnormalities including insulin resistance and diabetes." (PMID 32491965, 2020). "Treatment with Ga reproducibly decreased hepatic TG contents and attenuated insulin resistance, causing significant reductions in blood levels of glucose, insulin and leptin." (PMID 32792584, 2020). "The higher adiposity and the leptin-resistant genotype of the Iberian breed, with predisposition to insulin resistance and dyslipidemia, were also evident in the IB × IB offspring, which showed high plasma levels of fructosamine, cholesterol and triglycerides." (PMID 33291637, 2020). "Among African Americans in the Jackson Heart Study the association of leptin with incident type 2 diabetes was mediated by insulin resistance." (PMID 32131811, 2020). "The REE was also strongly associated with BMI (p < 0.00001), leptin (p < 0.001), insulin concentration (p < 0.001), and insulin resistance (p < 0.001)." (PMID 32651404, 2020). "Increased leptin levels are associated with insulin resistance, which, in turn, can lead to hyperinsulinemia." (PMID 33362710, 2020). "In the current study, we investigated the relationship between TMAO and deficits in synaptic plasticity in an Alzheimer’s model (3×Tg-AD) and insulin resistance (Leptin deficient db/db) mouse by measuring plasma and brain levels of TMAO." (PMID 32903435, 2020). "In our study, high leptin-adiponectin ratio was associated with increased risk of insulin resistance." (PMID 33299020, 2020). "High levels of leptin are associated with insulin resistance, hypothalamic inflammation, and disturbances in hemostatic factors, which are all risk factors for the development of hypertension, metabolic syndrome, or other cardiovascular diseases." (PMID 32655492, 2020). "Recently, our group reported on the role of several adipokines (adiponectin, leptin, resistin, and visfatin) in patients with HS and investigated the possible associations with insulin resistance, HS risk, and disease severity." (PMID 32992947, 2020). "This is also in agreement with another study showing that very low levels of leptin, too low to cause weight loss, can still correct hyperglycemia and insulin resistance in ob/ob mice." (PMID 32452759, 2020). "Similar to the other studies, our results show that BMI has a meaningful effect on insulin resistance due to the higher leptin levels in obese patients, so weight loss is considered as an important strategy in increasing insulin sensitivity." (PMID 33680012, 2020).
Insulin resistance (continued). "Targeting Fabp4 with an inhibitor can significantly improve insulin resistance in leptin-deficient ob/ob mice." (PMID 33603666, 2020). "The study also found that adjustment for insulin resistance abolished the association between leptin and type 2 diabetes, an indication that the association between leptin and incident type 2 diabetes was mediated by insulin resistance." (PMID 32131811, 2020). "In this study, we aimed to: (i) investigate the association between adiponectin and leptin with insulin resistance in patients with liver cirrhosis, and (ii) assess the influence of disease severity on insulin resistance and metabolic status." (PMID 32092909, 2020). "This study aimed to investigate the association between adiponectin and leptin with insulin resistance in cirrhotic patients and to assess the influence of disease severity on insulin resistance and metabolic status." (PMID 32092909, 2020). "Elevated leptin levels are associated with insulin resistance, hypertension, and cardiac hypertrophy." (PMID 32947606, 2020). "Accumulation of the lipids in the cells causes a chronic inflammation, up-regulates leptin expressions, and augments insulin resistance with the resultant dysfunctions in the kidney tubular endothelial cells." (PMID 32405364, 2020). "Insulin resistance was detected in 83% of subjects and associated with increased leptin, fasting plasma glucose and body mass index, and lower triglyceride levels." (PMID 32092909, 2020). "Differences by sex were also present, with male participants showing an association between leptin and incident type 2 diabetes mediated by insulin resistance." (PMID 32131811, 2020). "As such, differences in molecular tumor traits between study populations probably cannot explain the previously reported varying results for insulin-resistance biomarkers and leptin in relation to CRC risk." (PMID 32210264, 2020). "Correlations of IL-6, leptin and TNF-α with diabetes have been explored extensively, and most of these studies obtained results similar to ours that TNF-α, IL-6 and leptin were positively associated with insulin resistance or secretion." (PMID 33292292, 2020). "Circulating leptin levels were significantly increased in insulin resistance, which is associated with cardiac dysfunction." (PMID 33041846, 2020). "Both animals and humans with genetic deletions or mutations of either leptin or leptin receptor develop insulin resistance and a severe obese phenotype in postnatal life." (PMID 33114326, 2020). "They found that the level of circulating RBP4 is linked more specifically with insulin resistance than that of other adipokines such as leptin and adiponectin." (PMID 31147589, 2019). "By contrast leptin, another adipocyte-derived factor, parallels the degree of adiposity and is associated with insulin resistance." (PMID 31484347, 2019). "Elevated leptin levels also contribute to insulin resistance and show a positive correlation to the risk of cardiovascular diseases and metabolic syndrome." (PMID 31438590, 2019). "On the other hand, insulin resistance has been associated with leptin resistance and a reduction of plasma adiponectin, which is reverted by the simultaneous administration of leptin and adiponectin." (PMID 31489938, 2019). "High levels of leptin, associated with reduction in its activity, are known to lead to severe insulin resistance." (PMID 30911344, 2019). "Many studies indicated that multiple adipokines, such as adiponectin and leptin were involved in the occurrence and development of insulin resistance, possibly associated with many complications." (PMID 31803062, 2019). "Prevention of knee damage was associated with a normalization of insulin resistance, leptin levels, dyslipidemia, gut microbiota, and endotoxemia in the HFS-fed rats." (PMID 30846801, 2019). "Leptin is mainly produced by adipocytes and is associated with waist circumference, insulin resistance, and MetS." (PMID 31824416, 2019).
Insulin resistance (continued). "The systemic levels of leptin are also positively correlated with body mass index, and are associated with the development of insulin resistance." (PMID 31405033, 2019). "A few reports exist which demonstrate an improvement in insulin resistance in leptin-deficient ob/ob mice, while other studies supplementing food with antioxidants (e.g. apple polyphenol extracts or melatonin) have failed to report an effect on food intake." (PMID 31309261, 2019). "A strong association between levels of leptin, insulin and homeostatic model assessment of insulin resistance index (HOMA-IR) was also found in GD1 subjects." (PMID 31791361, 2019). "Some studies have found upregulated expression of IRS1, IRS2 in PCOS patients, and the circulating Leptin levels have been directly correlated with insulin resistance, which frequently is associated with PCOS." (PMID 32038578, 2019). "On the other hand, increased leptin concentrations during puberty were found to be a reliable indicator of insulin resistance associated with increasing age." (PMID 30704061, 2019). "Excessive leptin production is associated with high BMI and insulin resistance in T2DM, and as expected, HFD-fed WT mice exhibited a marked increase in plasma leptin compared with mice on control diet." (PMID 31379826, 2019). "In these patients, the combination of deficient adipose mass and low leptin level promotes metabolic dysfunction, including hypertriglyceridemia, severe fatty liver, insulin resistance, and, in most cases, diabetic glucose tolerance curves." (PMID 30357355, 2019). "Previous studies have shown that low adiponectin and high leptin levels were associated with a pro-inflammatory state, insulin resistance and coronary artery calcium severity in adults." (PMID 30479668, 2018). "Leptin has also been implicated in the regulation of insulin secretion by pancreatic β-cells, as well as in peripheral insulin resistance." (PMID 29910742, 2018). "We also found that the diurnal variation of leptin and sweet recognition thresholds were negatively associated with the homeostatic model assessment of insulin resistance (HOMA-IR) scores in OW/Ob subjects." (PMID 29498693, 2018). "In contrast to leptin, there is a stronger association of adiponectin with insulin resistance than with adiposity." (PMID 30373146, 2018). "The ratio of leptin to adiponectin is positively associated with muscle strength in older adults and is a biomarker of atherosclerotic disease, insulin resistance, and metabolic syndrome in the general population." (PMID 29949600, 2018). "Association with GH clinical findings: LEP 2548AA genotype with BMI and 2548G allele with systemic BP; LEP 109 Lys/Lys genotype with BMI and Insulin resistance." (PMID 30618791, 2018). "Individuals with MetS generally present high circulating concentrations of resistin and leptin, inducing leptin resistance and a decrease in adiponectin associated with insulin resistance." (PMID 30400222, 2018). "Accumulation of visceral adipose tissue was associated with insulin resistance, increased circulating levels of leptin and reduced adipokine." (PMID 30359431, 2018). "The intake of foxtail millet caused a significant increase of serum leptin (p = 0.012), decrease of insulin resistance (p = 0.007), and marginal reduction of inflammation." (PMID 30326632, 2018). "Our data supports that early gestational leptin is associated to state of insulin resistance and β-cell function." (PMID 30123262, 2018). "Primary defects in the development and differentiation of adipose tissues cause a reduction in the leptin levels, which results in prominent insulin resistance and subsequent metabolic abnormalities resembling metabolic syndrome." (PMID 30545408, 2018). "Summary of presented evidence that obstructive sleep apnea and its components are associated with decreased glycemic control, insulin resistance, increased leptin, and decreased chemosensitivity." (PMID 30127766, 2018).
Insulin resistance (continued). "When exposed to IH, rodents with deficient leptin signaling have exacerbated insulin resistance and increased cardiovascular impairments including endothelial dysfunction." (PMID 30127766, 2018). "The increased fat mass in obese was associated with higher levels of leptin and lower levels of adiponectin which is in agreement with the observed insulin resistance." (PMID 30183740, 2018). "Systemic levels of leptin positively correlate with both BMI and waist circumference, and are associated with the development of insulin resistance." (PMID 29760587, 2018). "Malfunction of leptin signaling, such as mutation in either leptin or leptin receptor, leads to fatty liver in association with insulin resistance in mice." (PMID 29312618, 2017). "In humans, previous studies investigating the associations between DM, insulin resistance, and leptin have been reported." (PMID 29088261, 2017). "The objective of this study was to investigate the influence of maternal and fetal common variants in the LEP gene on plasma glucose, insulin values, and insulin resistance in the fasted state among pregnant women." (PMID 29255202, 2017). "Elevated leptin concentrations are associated with adiposity and insulin resistance and it has been reported that individuals with the AA genotype ofLEPRrs1137100 showed higher concentrations than the G allele carriers." (PMID 28699988, 2017). "Nevertheless, we have shown that the bioactive leptin levels were strongly associated with selected insulin secretion and insulin resistance indices superior to immunoreactive leptin levels." (PMID 28542631, 2017). "Others have found that lower mid-pregnancy leptin levels are associated with reduced insulin resistance." (PMID 28577545, 2017). "Taken together, these results suggest that leptin, insulin, and insulin resistance are associated with cholelithiasis." (PMID 29088261, 2017). "The associations of leptin levels with insulin resistance and diabetes are overall inconsistent as the positive, inverse, and null associations have been reported previously." (PMID 28786989, 2017). "Both serum adiponectin and leptin were inversely associated with β-cell function, whereas only serum adiponectin was inversely associated with insulin resistance." (PMID 28786989, 2017). "In a previous study conducted in the same population of the present study, leptin levels were positively associated with insulin resistance after adjusting for sex, age, and BMI Z-score." (PMID 27598976, 2017). "It further suggests that hot flash association with insulin resistance is dependent on the combination of leptin and adiponectin variables." (PMID 28448547, 2017). "In the present study, it was shown that melatonin oral supplementation, at the dose of 100 mg/kg/day for 8 weeks, attenuated cardiac hypertrophy and adaptive remodeling in leptin-deficient (ob/ob) mice at 13 weeks of age, before overt insulin resistance." (PMID 29206172, 2017). "In this study we first investigated the effects of metformin on NAFLD in ob/ob obese mice, which develop hyperglycemia, insulin resistance (IR), hypertriglyceridemia and fatty livers owing to an inherited deficiency of the appetite-suppressing hormone, leptin." (PMID 29312569, 2017). "Excessive production of leptin is a consequence of resistance to its effect on target organs, and increased levels are associated with high BMI and insulin resistance in type 2 diabetes patients (T2DM)." (PMID 28068986, 2017). "In a recently published study, our group demonstrated that leptin is positively associated with insulin resistance in prepubertal children after adjusting for sex, age, and body mass index (BMI) Z-score." (PMID 27598976, 2017). "This is the first study with the aim to compare the associations of bioactive and immunoreactive leptin levels with selected parameters of insulin secretion and insulin resistance." (PMID 28542631, 2017).
Insulin resistance (continued). "For instance, in obese patients who are at risk of insulin resistance and thus metabolic syndrome, secretion of adiponectin by hypertrophic adipocytes is reduced, while that of leptin is increased." (PMID 28878827, 2017). "The aim of the study was to determine the role of adiponectin, leptin and resistin in various types of dementia and to investigate their association with inflammatory markers, insulin resistance and abdominal obesity." (PMID 28421328, 2017). "Compared to immunoreactive leptin, bioactive leptin showed similar and slightly better statistical associations with indices of insulin resistance in correlation and multivariate analyses." (PMID 28542631, 2017). "These mice also develop peripheral neuropathies, reduced plasma leptin levels and insulin resistance associated with a reduction of 50–90% in white and brown fat pad mass." (PMID 28606124, 2017). "The overexpression of miR-375 has also been reported in pancreatic islets of leptin-deficient ob/ob mice, a model of severe insulin resistance and increased islet mass, was 30% higher than normal controls." (PMID 29182561, 2017). "Both serum levels of adiponectin and leptin were inversely associated with β-cell function, but the inverse association with insulin resistance was found only for serum adiponectin." (PMID 28786989, 2017). "Depression has been shown to be associated with elevated leptin levels, low-grade inflammation and insulin resistance." (PMID 29190710, 2017). "Since SOCS1 and SOCS3 have been implicated in the development of leptin and insulin resistance, we further evaluated the mRNA expression level of these genes." (PMID 29025435, 2017). "The results indicate that both leptin and adiponectin are linked to the association between hot flashes and insulin resistance in postmenopausal women." (PMID 28448547, 2017). "Our results complement this notion by showing that up-regulated inflammation-related genes were closely associated with insulin resistance, serum adiponectin and leptin also in normoglycemic individuals, even after adjusting for measures of adiposity." (PMID 27080554, 2016). "The beneficial effects of creosote bush ethanolic extract in the HFD hamster model were a reduction of insulin resistance, associated with lower serum insulin and leptin, lower hepatic lipid peroxidation and higher liver antioxidant capacity." (PMID 27445827, 2016). "In other reports insulin resistance increases with hypoxia in genetically leptin deficient obese mice, respiratory conditions, and healthy humans." (PMID 27274997, 2016). "Recently, GlycA was associated with greater leptin to adiponectin ratios, an indicator of dysfunctional adipose tissue, leptin resistance, and insulin resistance, in subjects with metabolic syndrome or type 2 diabetes." (PMID 27067270, 2016). "There is a correlation between insulin resistance and an elevated risk for AD development and studies conducted in obese leptin-resistant mice showed that Metformin attenuated AD-like neuropathology and biological markers." (PMID 27467571, 2016). "PPARγ2 deletion in the leptin deficient ob/ob background resulted in decreased fat mass, dyslipidemia, β-cell failure and insulin resistance." (PMID 27483259, 2016). "Insulin resistance in pregnancy has been particularly associated with adiponectin and leptin, which are secreted only by the adipose tissue, and IL-6 and TNF-α, which are also secreted by the adipose tissue and other cells." (PMID 27651836, 2016). "The leptin-deficient ob/ob mice, characterized by hyperphagia-induced insulin resistance, are a well-established model for obesity." (PMID 27623749, 2016). "High leptin levels have been widely recognized as an independent cardiovascular risk factor associated with insulin resistance." (PMID 26873309, 2016).